FRGCA (FOXM1-regulated, gastric cancer associated)
Synonyms: LncRNA-AP001631.9
Gene: Long non-coding RNA gene on chromosome 21 (43,134,007 to 43,141,679, reverse strand). Ensembl gene ENSG00000236663.
Diseases named in the same sentence as FRGCA in open-access papers:
FRGCA is named in the same sentence as 2 diseases in open-access papers, as found by Europe PMC text mining. Sharing a sentence is not in itself a finding about the gene and the disease. The quoted sentences say what the papers report.
gastric cancer (1 paper, 2017). A primary or metastatic malignant neoplasm involving the stomach. "We found 3 novel lncRNAs in the top 20 (FRGCA at 3, MALAT1 at 13 and MEG3 at 20) that were recently associated with gastric cancer." (PMID 27992375, 2017). "Knockdown and overexpression experiments of FRGCA showed that it played a critical role in gastric cancer progression and was a potential therapeutic target." (PMID 27992375, 2017).
FRGCA also shares sentences with these, for which no sentence is quoted: colon adenocarcinoma (1 paper).